SAMHD1 (SAM and HD domain containing deoxynucleoside triphosphate triphosphohydrolase 1)
Diseases named in the same sentence as SAMHD1 in open-access papers (continued):
Sharing a sentence is not in itself a finding about the gene and the disease.
HIV-1 infection (continued). "At 2 and 3 dpi, THP-1 Ctrl and SAMHD1 KI cells showed significantly less Δψm, which was further decreased by HIV-1 infection, compared to SAMHD1 KO and Lvx cells." (PMID 40434097, 2025). "Our findings reveal a regulatory mechanism by which SAMHD1 enhances apoptosis induced by HIV-1 infection, suggesting a previously unrecognized function of SAMHD1 in modulating cellular responses to viral infection." (PMID 40434097, 2025). "It would be of interest to understand if SAMHD1/MxB-mediated restriction function suppresses HIV-1 infection, pathogenesis, and persistence in vivo." (PMID 40277359, 2025). "In our previous study, SAMHD1 inhibited HIV-1 infection at 1 and 2 dpi in PMA-differentiated THP-1 macrophage-like cells with increased SAMHD1 protein expression." (PMID 40434097, 2025). "In this study, we aim to bridge this knowledge gap by investigating the functional significance of SAMHD1 in regulating apoptosis during HIV-1 infection of immune cells." (PMID 40434097, 2025). "In this study, we identified that SAMHD1 enhances apoptosis induced by HIV-1 infection in THP-1 cells through the mitochondrial pathway." (PMID 40434097, 2025). "Similar HIV-1 infection levels at 2 dpi or later in dividing THP-1 cells with or without endogenous SAMHD1 provide an appropriate model to investigate the function of SAMHD1 in HIV-1-induced apoptosis in monocytic cells." (PMID 40434097, 2025). "In this study, we found that endogenous SAMHD1 enhances apoptosis induced by HIV-1 infection in THP-1 cells through the mitochondrial pathway." (PMID 40434097, 2025). "Together, these data suggest that SAMHD1 enhances apoptosis induced by HIV-1 infection through the mitochondrial pathway by depolarizing mitochondria and cytosolic release of Cyto c." (PMID 40434097, 2025). "Collectively, the results indicate that efficient restriction of HIV-1 replication by SAMHD1 in macrophage-like cells downregulates SAMHD1-enhanced apoptosis by HIV-1 infection." (PMID 40434097, 2025). "This suggests a previously unrecognized role of SAMHD1 in modulating cellular responses to HIV-1 infection." (PMID 40434097, 2025). "Our previous study demonstrated that SAMHD1 inhibited single-cycle HIV-1 infection in dividing THP-1 cells at 1 day post-infection (dpi), but not at 2 dpi." (PMID 40434097, 2025). "To investigate the role of BIK in SAMHD1-enhanced apoptosis, we knocked out BIK expression in THP-1 SAMHD1 Ctrl and SAMHD1 KO cell lines and then measured HIV-1 infection and apoptosis." (PMID 40434097, 2025). "In this way, SAMHD1 limits HIV-1 infection by restricting reverse transcription, leading to reduced viral replication efficiency (11, –, 16)." (PMID 40586616, 2025). "SAMHD1 is an intrinsic limiting factor that effectively prevents HIV-1 infection in macrophages, dendritic cells, and resting CD4+ T cells." (PMID 39240132, 2024). "The HIV-1 infection-blocking ability of SAMHD1 correlates with its dNTPase activity (10, –, 12), which decreases dNTP levels in non-cycling cells." (PMID 39162568, 2024). "During HIV-1 infection, SAMHD1 recognizes the incoming HIV-1 core and sequesters viral components onto MX2-formed molecular traps." (PMID 39240132, 2024). "In this study, we identify a novel mechanism by which SAMHD1 exerts its inhibitory effect on HIV-1 infection postviral cDNA synthesis through interactions with MX2 and the HIV-1 core protein." (PMID 38888311, 2024). "Previous investigations revealed that phosphorylation at T592 governs both the ability of SAMHD1 to prevent HIV-1 infection and the flexibility of the SAMHD1 C-terminal domain, particularly those residues that follow the HD domain." (PMID 39162568, 2024). "The dNTPase activity is known to be indispensable for the ability of SAMHD1 to suppress HIV-1 infection." (PMID 39240132, 2024).
HIV-1 infection (continued). "SAMHD1 acetylation at K580 was also found to be important for its ability to block HIV-1 infection, as our mutagenesis studies revealed that replacing K580 with R, Q, A, or E residues inhibited this ability." (PMID 39162568, 2024). "This mechanistic insight into SAMHD1 updates the conventional model of SAMHD1-mediated suppression of HIV-1 infection, which was attributed to the regulation of dNTP levels, by elucidating its direct impact on HIV-1 replication." (PMID 39240132, 2024). "Our research underscores the significance of these modifications, demonstrating that acetylation at residue K580 is indispensable for SAMHD1's efficacy in blocking HIV-1 infection." (PMID 39162568, 2024). "In SAMHD1-null U937 cells, treatment with IFNα had only a minor effect (1.6-fold reduction) on HIV-1 infection." (PMID 38888311, 2024). "The activity of intrinsic antiviral defenses, such as SAMHD1 (discussed in Section 4.2), play a role in resisting HIV-1 infection, but a slew of other mechanisms remains incompletely understood." (PMID 39205287, 2024). "In contrast, depletion of endogenous T592A mutant SAMHD1 significantly increased HIV-1 infection rates (Clone #1 and #2 P < 0.0001, n = 3, one-way ANOVA)." (PMID 37800914, 2023). "To better understand the role of IRF7 on SAMHD1-mediated suppression of IFN-I signaling during HIV-1 infection, we first examined the effect of IRF7 KO on HIV-1 infection." (PMID 37328105, 2023). "As expected, SAMHD1 KO resulted in significantly increased HIV-1 infection compared with Ctrl cells." (PMID 37328105, 2023). "The HIV Vpx/CUL4/DCAF1/RBX1 complex relieves inhibition of HIV-1 infection of macrophages by mediating SAMHD1 protein degradation." (PMID 38005838, 2023). "Sterile alpha motif and HD domain-containing protein 1 (SAMHD1) restricts human immunodeficiency virus type 1 (HIV-1) infection by reducing the intracellular dNTP pool." (PMID 37328105, 2023). "It would be of interest to investigate perturbations in error-prone gap repair and SAMHD1 in gut B cells during chronic HIV-1 infection in follow-up work." (PMID 35938870, 2022). "SAMHD1 protein is known to restrict HIV-1 infection in cells of the myeloid lineage, such as monocytes/macrophages and DCs, by inhibiting the synthesis of viral DNA." (PMID 36359340, 2022). "Among the most potent restriction mechanisms of HIV-1 infection in DCs is SAM domain HD domain-containing protein 1 (SAMHD1)." (PMID 35204813, 2022). "For example, SAMHD1, a dNTP-degrading phosphohydrolase and intracellular enzyme that restricts HIV-1 infection of myeloid cells, along with the purine nucleoside phosphorylase PNP affect survival rates of dGuo-exposed cells." (PMID 35355997, 2022). "Our data suggest that the TRAF6-TAK1 axis contributes to SAMHD1-mediated suppression of NF-κB activation and HIV-1 infection." (PMID 33177202, 2021). "Genetic ablation of the restriction factor SAMHD1 increased HIV-1 infection >50-fold, demonstrating the power of this system for genotype-phenotype interrogation." (PMID 33979618, 2021). "Altogether, these results suggest that SAMHD1 contributes to suppressing the innate immune responses initiated through the TRAF6-TAK1 signaling complex during single-cycle HIV-1 infection." (PMID 33177202, 2021). "The ability of Vpx to increase HIV-1 infection efficiency in MDMs can be dissociated from its ability to augment ISG responses by overcoming SAMHD1 restriction in these cells." (PMID 33563288, 2021). "Vpx potentiates ISG responses during HIV-1 infection independently of SAMHD1 degradation, but requires the interaction with the ubiquitin-proteasome system, implicating another host factor targeted for degradation by Vpx." (PMID 33563288, 2021). "We targeted the host viral restriction factor SAMHD1, which blocks lentiviral infection (including HIV-1 infection) by depleting intracellular pools of deoxynucleoside triphosphates (dNTPs) needed for reverse transcription." (PMID 33979618, 2021).
HIV-1 infection (continued). "Our research reveals a new negative regulatory mechanism by which SAMHD1 participates in the maintenance of cellular homeostasis during HIV-1 infection and inflammation." (PMID 33177202, 2021). "A luciferase assay conducted 24 h postinfection (hpi) showed a 13-fold increase of HIV-1 infection in SAMHD1 KO cells compared to control cells, which were reduced 1.5-fold or 1.8-fold by 5Z or Takinib treatment, respectively." (PMID 33177202, 2021). "Crucially, the TLR4 inhibitor TAK242 completely prevented G0 arrest and SAMHD1 phosphorylation changes, restoring HIV-1 infection." (PMID 32209460, 2020). "We showed that TLR-4 pathway activation in MDM and G1-to-G0 transition was accompanied by the dephosphorylation/activation of SAMHD1 and blocking of HIV-1 infection in macrophages." (PMID 32751972, 2020). "As reported by other groups, depletion of SAMHD1 by treatment of MDMs with Vpx-containing SIV VLPs (abbreviated Vpx(+)) resulted in a marked (up to 10-fold) increase of HIV-1 infection, apparently due to increased cytoplasmic dNTP levels." (PMID 33143125, 2020). "How SAMHD1 plays a role in triggering an immune response following HIV-1 infection is still controversial." (PMID 32244340, 2020). "From these experiments we conclude that MyD88 activation is insufficient to induce G0 arrest, dephosphorylation of SAMHD1, and blockade of HIV-1 infection." (PMID 32209460, 2020). "We have shown previously that the restriction of HIV-1 infection in G0 MDMs can be completely lifted by SAMHD1 depletion." (PMID 32209460, 2020). "The addition of viral-like particles (VLPs) carrying Vpx enhances HIV-1 infection and promotes cGAS-dependent innate immune response through degradation of SAMHD1 and possibly other undefined mechanisms." (PMID 31968566, 2020). "Specifically, after different stimuli, phosphorylation of SAMHD1 modifies its ability, leading to the inhibition of HIV-1 infection in macrophages." (PMID 33224139, 2020). "This is because macrophages in a G1 state switch off the antiviral restriction factor SAMHD1 by phosphorylation, thereby allowing productive HIV-1 infection." (PMID 32751972, 2020). "Recently, it has been shown that DNA damage (mediated by topoisomerase inhibitors used in cancer treatment—e.g., etoposide—or by UV light) is connected to the SAMHD1-dependent inhibition of HIV-1 infection in primary human monocyte-derived macrophages." (PMID 32751972, 2020). "All SAMHD1 mutants identified in AGS patients lost their ability to block HIV-1 infection except for G209S." (PMID 32244340, 2020). "Human DCs express HIV-1 restriction factors among which is SAM domain and HD domain-containing protein 1 (SAMHD1), the major protein responsible for the relative resistance of DCs to HIV-1 infection." (PMID 32181159, 2020). "We have discovered that this is because macrophages in a G1 state switch off the antiviral restriction factor SAMHD1 by phosphorylation, thereby allowing productive HIV-1 infection." (PMID 32751972, 2020). "Even though macrophages are typically portrayed as cells resistant to HIV infection due to low dNTP levels and the restriction factor SAMHD1, others and we have shown that macrophages can regulate dNTP levels and allow productive HIV-1 infection." (PMID 32751972, 2020). "Collectively, these results suggest that while reverse transcription promotes cytoplasmic uncoating, the improvement of HIV-1 infection in SAMHD1-depeleted MDMs is likely due to more efficient vDNA synthesis and completion in the nucleus." (PMID 33143125, 2020). "Activation of the pathway leads to dephosphorylation of SAMHD1 at a T592 and a specific block to HIV-1 infection that is significantly counteracted by SAMHD1 depletion." (PMID 32209460, 2020). "The restriction of HIV-1 infection by SAMHD1 occurs via its ribonuclease activity and phosphorylation of SAMHD1 inhibits this restrictive function." (PMID 31220191, 2019).
HIV-1 infection (continued). "SAMHD1, a dNTP triphosphohydrolase, restricts productive HIV-1 infection in dendritic cells, myeloid cells and resting CD4+ T cells." (PMID 31220191, 2019). "In the case of HIV-1 infection, it has been described that SAMHD1 impairs cell-to-cell transmission of HIV-1 in moDCs limiting innate immune responses." (PMID 31426525, 2019). "We have previously shown that the down-regulation of SAMHD1 expression during T-cell activation and differentiation renders CD4+ T cells susceptible to HIV-1 infection." (PMID 31220191, 2019). "In monocyte-derived macrophages, IL-12 and IL-18 treatments lead to the overexpression of SAMHD1 which renders cells resistant to HIV-1 infection." (PMID 31426525, 2019). "Because SAMHD1 dephosphorylation activates its restriction activity, this result predicted that NCS treatment would decrease the susceptibility of MDMs to HIV-1 infection." (PMID 29515139, 2018). "Human SAMHD1 (hSAMHD1) is a retroviral restriction factor that blocks HIV-1 infection by depleting the cellular nucleotides required for viral reverse transcription." (PMID 29379009, 2018). "Expanding our study beyond the natural biology of HIV-1 infection, we show that SAMHD1 activity can be targeted by several FDA-approved anti-cancer TKIs." (PMID 29764952, 2018). "Our recent study showed that CDK2 activity was inhibited in peripheral blood mononuclear cells obtained from patients with sickle cell disease, which led to the activation of SAMHD1 and inhibition of ex vivo HIV-1 infection." (PMID 29792216, 2018). "We show that treatment of MDMs with neocarzinostatin, a compound that introduces double strand breaks (DBS) in genomic DNA, results in the decrease of phosphorylated SAMHD1, activating its antiviral activity and blocking HIV-1 infection." (PMID 29515139, 2018). "The stimulatory effect of Vpx-mediated SAMHD1 degradation on HIV-1 infection efficiency in macrophages—presumably through increasing intracellular dNTP levels—is well documented." (PMID 30423802, 2018). "We investigated the role of SAMHD1 and its phospho-dependent regulation in the context of HIV-1 infection in primary human monocyte-derived macrophages and the ability of various interferons (IFNs) and pharmacologic agents to modulate SAMHD1." (PMID 29764952, 2018). "If SAMHD1 dephosphorylation and consequent dNTP depletion contributed to the observed block in HIV-1 infection induced by IFN-γ, then Vpx should confer at least some level of resistance." (PMID 30132758, 2018). "Few studies have addressed the potential role of SAMHD1 in connecting innate and adaptive immune responses in HIV-1 infection." (PMID 30574147, 2018). "Strikingly, as HeLa or activated primary CD4+ T cells enter the G1 phase, pronounced reduction of RT products is observed upon HIV-1 infection dependent on the presence of dephosphorylated SAMHD1." (PMID 29884836, 2018). "The sterile alpha-motif and histidine-aspartate domain-containing protein 1 (SAMHD1) is a dNTP phosphohydrolase that blocks HIV-1 infection by depleting cellular dNTPs." (PMID 29379009, 2018). "Here, we provide an overview of the cell-intrinsic HIV-1 restriction activity of APOBEC3G, SAMHD1, Tetherin, and TRIM5α proteins, focusing on their complex interplay with innate and adaptive immune responses in the context of HIV-1 infection." (PMID 30574147, 2018). "The triphosphohydrolase activity of the host protein SAMHD1 is important for maintaining low dNTP levels in macrophages, and the protein was recognized as an important host cell restriction factor of HIV-1 infection." (PMID 30423802, 2018). "The structural and functional studies of SAMHD1 connect the physiology of HIV-1 infection to the innate antiviral response and the dynamic regulatory mechanisms in cells." (PMID 29176984, 2017).
HIV-1 infection (continued). "Recent work has revealed a crucial role for the CDK-mediated regulation of SAMHD1 in determining permissivity of myeloid cells to HIV-1 infection." (PMID 29056936, 2017). "Although the accepted consensus is that SAMHD1 restricts HIV-1 infection through the depletion of intracellular dNTPs, several studies suggested the existence of an additional yet-undiscovered mechanism of SAMHD1-mediated retroviral restriction." (PMID 29176984, 2017). "SIV VLPs were used to deliver SIV accessory protein viral protein x (Vpx) to inhibit the restriction factor SAMHD1, thereby allowing HIV-1 infection." (PMID 29056936, 2017). "Vpx-mediated degradation of SAMHD1 in DCs leads to enhanced HIV-1 infection, and studies in primary MDMs and MDDCs indicate that Vpx-mediated SAMHD1 degradation results in cGAS stimulation and IRF3 activation." (PMID 29176984, 2017). "HIV-1 suppresses TLR-induced maturation of DCs independent of SAMHD1 expression, although Vpx-mediated depletion of SAMHD1 enhanced the effect of HIV-1 infection on lipopolysaccharide-induced DC maturation." (PMID 29176984, 2017). "In this way, Vpx provided either packaged into VLPs for co-transduction or stably expressed in cell lines, is able to counteract SAMHD1 restriction of HIV-1 infection." (PMID 29056936, 2017). "In myeloid-derived dendritic cells and macrophages as well as resting T-cells, SAMHD1 blocks HIV-1 infection through this dNTP triphosphohydrolase activity by reducing the cellular dNTP pool to a level that cannot support productive reverse transcription." (PMID 28220857, 2017). "This is shown with the D137N mutant of SAMHD1, which possesses RNase activity but specifically loses phosphohydrolase activity and is still able to restrict HIV-1 infection." (PMID 29379496, 2017). "The molecular biology of HIV-1 infection in macrophages is influenced by the presence of the host cell restriction factor SAMHD1, which is regulated by phosphorylation by cyclin dependent kinases, the catalytic proteins responsible for cell cycle progression." (PMID 27541004, 2016). "SAMHD1 phosphomimetic mutants T592D and T592E lost the ability to block HIV-1 infection, which is in agreement with previous observations." (PMID 27511536, 2016). "find that SAMHD1, which blocks HIV-1 infection in myeloid cells, prevents innate sensing of infection via cGAS/STING." (PMID 27477283, 2016). "Because myeloid cells and CD4+ T cells from human peripheral blood are the primary target cells during HIV-1 infection, to this end, we examined SAMHD1 expression in these cells." (PMID 27922067, 2016). "Vpx degrades SAMHD1, overcoming the block to HIV-1 infection of resting T cells and primary monocytes allowing us to test how well the drug blocks infection and to investigate its antiviral mechanism." (PMID 27905985, 2016). "Depletion of SAMHD1 by Vpx in cultured human cells not only facilitates HIV-1 infection but also results in the induction of an antiviral response." (PMID 27477283, 2016). "Since the regulation of SAMHD1 expression by immune activation is still obscure, we thus initiated experiments to investigate SAMHD1 expression in association with in vivo HIV-1 replication and immune activation during chronic HIV-1 infection." (PMID 27922067, 2016). "Monocytes, the primary myeloid cell-type in peripheral blood, are resistant to HIV-1 infection as a result of the lentiviral restriction factor SAMHD1." (PMID 27905985, 2016). "Although the restriction mechanisms of SAMHD1 have been well-described, SAMHD1 expression and Vpx-mediated SAMHD1 degradation during chronic HIV-1 infection were poorly understood." (PMID 27922067, 2016). "Recently, it has been shown that SAMHD1 can restrict HIV-1 infection also through degradation of viral RNA." (PMID 25608886, 2015). "Tetramer-disrupting mutations abolish dNTPase activity as well as the ability of SAMHD1 to restrict HIV-1 infection." (PMID 26416562, 2015).